ENSG00000307700 (novel transcript, antisense to ADAM11 and DBF4B and LOF:DBF4B)
Gene: Long non-coding RNA gene on chromosome 17 (44,735,952 to 44,759,501, reverse strand). Ensembl gene ENSG00000307700.
Gene Ontology:
Biological process: SRP-dependent cotranslational protein targeting to membrane, signal sequence recognition
Cellular component: signal recognition particle, endoplasmic reticulum targeting